S100B (S100 calcium binding protein B)
Diseases named in the same sentence as S100B in open-access papers (continued):
Sharing a sentence is not in itself a finding about the gene and the disease.
tumor (continued). "Three-dimensional imaging of colonic adenocarcinomas revealed that S100β+ GFAP+ enteric glial cell bodies and processes extensively infiltrate the tumor mass, including direct interactions between EGCs and tumor-associated macrophages within the CRC microenvironment." (PMID 41463087, 2025). "It is important to note that the relationship between S100B levels and survival outcomes might be influenced by various factors, including tumor stage, treatment modalities, and patient characteristics." (PMID 40535809, 2025). "It was shown that serum S100B levels reflect tumor burden, correlate with treatment response, and might be useful in identifying the risk of recurrence." (PMID 40535809, 2025). "Circulating biomarkers—including conventional serologic markers (LDH, S100B), circulating tumor DNA (ctDNA), and small non-coding RNAs such as microRNAs (miRNAs)—offer complementary information that can anticipate therapeutic efficacy or resistance long before radiologic evidence becomes apparent." (PMID 41374434, 2025). "We speculate that S100B may serve as a tumor suppressor gene in TNBC, exerting its immune-activating role by activating CD8+ T cells." (PMID 40606662, 2025). "In addition, measurement of serum S100B levels has been shown to be useful in monitoring tumor response in patients receiving targeted therapy." (PMID 39272837, 2024). "Among PitNET subtypes, gonadotroph tumours had the most variable S100B distribution, though this may be partly due to our cohort composition." (PMID 35139928, 2022). "Following this validation, we analysed the number and the spatial distribution of FS cells through their S100B immunoreactivity, in a cohort of 54 patients with PitNETs (26 gonadotroph tumours, 20 tumours of the Pit1 lineage, and 8 corticotroph tumours) and 4 normal APG samples." (PMID 35139928, 2022). "Correlation analysis of the 20 tumour areas further confirmed that the percentage of S100B + cells was positively and strongly correlated with the percentage of FSH + cells (Spearman’s rho = 0.78, adjusted p = 0.0007) and of ERα + cells (Spearman’s rho = 0.76, adjusted p = 0.001)." (PMID 35139928, 2022). "In the current study, GO and pathways enrichment analysis results indicate that S100B and its co-expressed genes are involved in tumor-related immune response pathways, including NF-kappa B signaling, T cell and B cell receptor signaling pathway in human cancer." (PMID 35368338, 2022). "Interestingly, the percentage of S100B + cells showed a moderate positive correlation with the percentage of ERα + cells in gonadotroph tumours." (PMID 35139928, 2022). "The identification of a heterogeneous spatial distribution of S100B + cells in individual gonadotroph tumours led us to question whether the spatial distribution of S100B + cells may be of functional relevance in these tumours." (PMID 35139928, 2022). "We conducted an interpatient and an intratumoural cartography of S100B + cells to gain insight into the potential functions these cells might have in gonadotroph tumours." (PMID 35139928, 2022). "However, the functions of S100B and its underlying mechanisms in HCC remain poorly understood, especially in the tumor microenvironment." (PMID 35368338, 2022). "We speculate that hypoxia contributes to S100B overexpression in immune cells and promotes cells invasion and tumor immune escape through regulation of S100B related gene expression in HCC." (PMID 35368338, 2022).
tumor (continued). "To further validate these associations, we confirmed the existence of gonadotroph tumour areas presenting either an enrichment in S100B, ERα, and FSH immunoreactivity, or a lack of immunoreactivity for the three markers." (PMID 35139928, 2022). "Numerous studies have reported that S100B is involved in tumor metastasis in many cancers." (PMID 35368338, 2022). "Additionally, GO/KEGG cluster analysis results indicated that co-expressed genes of S100B were involved in biological processes of immune response and multiple tumor immune-related signaling pathways in HCC." (PMID 35368338, 2022). "Moreover, S100B + cells were more widely spread in gonadotroph tumours (range 0.01–9.55%) compared to Pit1 (range 0–2.17%) and corticotroph tumours (range 0.007–3.42%)." (PMID 35139928, 2022). "Using whole-scan quantification of S100B IHC staining, we first confirmed an overall loss of S100B + FS cells in the majority of our PitNETs compared to normal APG and to adjacent APG, with 80% of these tumours having < 1% S100B + cells, and 35% having < 0.1% S100B + cells." (PMID 35139928, 2022). "The protein level of S100B was also higher in tumor tissues than that in normal tissues." (PMID 34837947, 2021). "The use of the biomarker S100B protein to determine non-traumatic, traumatic and tumor-associated brain damage is accepted practice." (PMID 34627354, 2021). "To determine whether 2XSB cells maintained the immunophenotype of the parent tumor, we stained 2XSB cells for S100β, Sox10 and nestin." (PMID 33707600, 2021). "A subset of tumor cells was immunoreactive for the intermediate filament nestin (30–70% of the cells in each field), much as was observed for the calcium binding protein S100β (30–70% positivity)." (PMID 33707600, 2021). "The expression of S100B mRNA was strikingly increased in tumor tissues compared with that in normal tissues, and S100B mRNA expression was negatively correlated with miR-1182 expression in tumor tissues." (PMID 34837947, 2021). "In the analyzed patients, rise of cytokine IL-6 as well as release of tumor marker S100B demonstrated oscillations with a frequency in the range of a few days, suggesting that weekly monitoring of these markers constitutes a minimal requirement in order to identify the expected effects." (PMID 32188047, 2020). "A parallel serum level increase of interleukin-6 and the tumor marker S100B could be identified in 13 patients, suggesting that the onset of tolerance breakage under checkpoint inhibition may be identified and measured." (PMID 32188047, 2020). "In 13 patients we could observe a parallel increase of tumor marker S100B and of the immune activation marker IL-6 in the serum." (PMID 32188047, 2020). "Finally, muscles of wild type and Ager−/− mice were injected with TNFα/IFNγ or S100B in a tumour‐free environment." (PMID 32159297, 2020). "Indeed, conditioned medium derived from LLC cells (LLC‐CM) or LLC tumour masses (LLC‐TM) contained significant amounts of S100B and HMGB1." (PMID 32159297, 2020).
tumor (continued). "Hence, rising serum levels of S100A8/A9 are likely to precede bulky tumor growth which finally leads to increases of S100B or LDH." (PMID 31806053, 2019). "S-100B has calcium-binding properties and it inhibits protein phosphorylation and cytoskeleton formation, which may favour tumour progression." (PMID 29492238, 2018). "In conclusion, identification of the adaptability network with S100β has the potential to provide new information regarding the response of the patient tumor to ongoing endocrine therapy and act as a companion diagnostic to increase the efficacy of combined tyrosine kinase inhibitor treatment." (PMID 28399921, 2017). "Immunostaining with epithelioid MPNST marker, S100β, showed strong expression in spindle-shaped tumor cells (2D’) while the mesenchymal marker, Vimentin, also showed extensive staining in tumor tissues of cdkn2a/b TALEN mRNA injected tp53e7/e7 mutant zebrafish (2E’)." (PMID 28903419, 2017). "S100b showed significant weaker staining in lymph nodes compared to primary tumours (p < 0.01)." (PMID 27853253, 2016). "For example, S100B is known to be upregulated in melanomas and is used as a tumor marker." (PMID 26097874, 2015). "Interestingly, S100B promotes cell cycling in the CNS and S100B levels are high in neuronal tumor cells as compared to normal parental cells." (PMID 25536222, 2014). "In addition, post-vaccination sCEACAM1 correlates with S100B, which sensitively reflects tumor mass." (PMID 22291846, 2012). "In advanced disease elevated levels of S100B also demonstrate a strong correlation with reduced survival as patients with stage III or IV disease and low S100B have shown statistically significant survival advantage compared to patients with elevated tumour marker." (PMID 21810220, 2011). "Finally, serum S100β levels correlated with the size of the tumour-brain contact surface, which was closely related to the dimension of the surgical trauma, and with postoperative CNS damage caused by neurosurgical manipulation." (PMID 17020600, 2006). "Similarly, S100B overexpression correlates with tumor growth and macrophage recruitment, and its decrease supports the hypothesis of reduced tumor aggressiveness." (PMID 41154863, 2025). "Thus, the association between elevated S100B levels and an increased risk of MBM development might be related to a more aggressive tumor biology." (PMID 40217072, 2025). "Studies confirmed that S100B may be considered a tumor marker." (PMID 39335163, 2024). "However, this marker has its limitations; for example, LDH levels do not associate as well as S-100B with the metabolic active tumor volume (evaluated via 18F-FDG PET/CT scans)." (PMID 38535074, 2024).
tumor (continued). "Hence, these observations confirmed the heterogeneous nature of gonadotroph tumours, and suggest that the heterogeneous distribution of S100B + cells might be of functional relevance within the TME of gonadotroph PitNETs." (PMID 35139928, 2022). "Moreover, the signature of S100B could reflect the infiltration characterization of different immunocytes in the tumor microenvironment." (PMID 35368338, 2022). "Interestingly, whereas most of the tumours analysed displayed a very low percentage of S100B + cells (43 tumours had < 1% of S100B + cells and 19 tumours < 0.1% S100B + cells), a small fraction of them had a higher percentage of S100B + cells reaching a maximum of 9.55%." (PMID 35139928, 2022). "In addition, our findings highlight the spatial relationships between the presence of FS cells and the proliferative capacity, as well as FSH and oestrogen receptor alpha (ERα) immunoreactivity of gonadotroph tumour cells, suggesting potential roles of S100B + cells in gonadotroph tumorigenesis." (PMID 35139928, 2022). "Research should also focus in the future on patient and tumor characteristics that may predict the sensitivity of S‐100B during follow‐up, with the aim of identifying patient subgroups in which S‐100B shows higher sensitivity, to maximize the effectiveness of this tool." (PMID 31468535, 2019). "Again, we used nestin, Sox2, βIII-tubulin and S100β to assess the cell differentiation state and found all tissues exhibited relatively high numbers of cells expressing nestin and S100β, but low numbers of cells expressed βIII-tubulin and Sox2, as expected for this type of tumour." (PMID 27541285, 2017). "Particularly, we also found that the relapsed/resistant tumor cells expressed a signature of “Schwann cell precursors (SCP)”51,52, characterized by high expression of S100b, Sox10, Plp1 and other genes." (PMID 40962798, 2025). "Astrocytes also respond to melanoma by activating NF-κB–TLR4 and P2X7 pathways when exposed to tumor-derived HMGB1, S100B, and ATP." (PMID 41463339, 2025). "The presence of enteric glia using S100B and GFAP staining in CRC tumor tissue and an increase compared to normal human colon tissue was previously shown by other groups in a limited number of human samples." (PMID 40580485, 2025). "Glial fibrillary acidic protein (GFAP)+/S100β+ astrocytes secrete PA, which induces tumor cell apoptosis and limits the activation of L1CAM to restrict tumor dissemination." (PMID 41429896, 2025). "Astrocytic endfeet surrounding the co-opted vessels respond to tumor-derived HMGB1, S100B, and extracellular ATP with a stimulation of NFκB-TLR4 and P2X7 signaling in astrocytes." (PMID 41463339, 2025). "The master transcriptional factors of MES state cells, such as c-MYC, PRRX1 and NOTCH1 were highly upregulated in the resistant tumor cells, together with the SCP marker S100B and stem cell markers KIT and SALL4." (PMID 40962798, 2025). "The marker genes S100B, PMEL, and MLANA showed significantly high expression in tumor cells in the SKCM_GSE115978_aPD1 dataset." (PMID 38911384, 2024). "Immunofluorescence staining of the cells shows that cells stably transmitted to 100 generations are positive for the specific IHC indexes MLANA, S100β, PNL2, TRP1, and TRP2, which is consistent with the results of the IHC indexes of canine tumor tissues." (PMID 38891124, 2024). "Several targets showed specifically higher expression in HET cases, including TIM3, BCL2, S100B, and CD44 (tumor ROI only), implying a more immunosuppressive microenvironment within these tumors." (PMID 38300710, 2024). "The AUC was the strongest in the model combining serum S100B, LDH, OPN, tumor localization, and T category." (PMID 38202181, 2023).
tumor (continued). "The tumor region of the CR patient indicated higher levels of VISTA, CD45, IDO1, and S100B while S473 expression was found to be decreased." (PMID 37153589, 2023). "First, in the univariate logistic regressions, the primary tumor location, American Joint Committee on Cancer (AJCC) 8th edition pT category, and serum S100B, LDH, and plasma OPN levels showed a significant effect on the probability of metastasis." (PMID 38202181, 2023). "In the protein level, the gene expression of HSP90AA1, NFKB2, PTK2 was upregulated in tumor tissues, and CLU, JAK2, MAP3K5, and S100B were downregulated in the normal tissues." (PMID 36323529, 2023). "For further validation of these prognostic markers, we analyzed S100B and SOX9 protein in an ONB tumor by IHC." (PMID 37377616, 2023). "Thus, S100B expression maybe result in the migration of immune cells in HCC tumor microenvironment." (PMID 35368338, 2022). "In contrast to the presumed specificity of S100B, a variety of tumours and cells originating from all germ layers can be induced to express S100 proteins, particularly S100A8, S100A9, S100A12 and S100B, as a result of oxidative stress and tissue inflammation." (PMID 35323240, 2022). "S100B is activated by hypoxia via HIF-1a dependent manner to promoter cell proliferation, invasion and metastasis under tumor hypoxic conditions." (PMID 35368338, 2022). "To refine this observation, we used histological sections in which both tumour and adjacent APG areas were present, and comparatively quantified the percentage of S100B + cells in individual patients." (PMID 35139928, 2022). "We found that the expressions of CCL1, FABP7, S100B, CTSW, and SEZ6 significantly decreased in the tumor tissue, the expression of CPLX2 and SPIB increased obviously in BC." (PMID 36581948, 2022). "Chondroitin sulfate and heparan sulfate strongly bind to RAGE and suppressed the colonization of lungs by tumor cells, and GM-1111 inhibited interactions between RAGE and CML, HMGB1, and S100B and exhibited anti-inflammatory activity." (PMID 34199060, 2021). "In order to assess the possible role of each drug on brain metastasis, eight protein/gene effectors known to have a more important role in brain metastasis than in primary tumours were considered: FGFR1; Ki-67, ROBO1; S100A7; S100B; SIRT1; SLIT2; and VEGFA." (PMID 33659043, 2021). "Serum levels of the RAGE ligands, S100B, and HMGB1 also were robustly increased in LLC‐bearing compared with untreated mice, likely released from tumour cells." (PMID 32159297, 2020). "RAGE, which is absent in adult healthy muscle, is re‐expressed in atrophying myofibers via p38 MAPK under the action of proinflammatory cytokines and elevated serum levels of S100B and HMGB1, released from tumour cells." (PMID 32159297, 2020). "We demonstrate that S100B and HMGB1 are able to induce muscle atrophy per se at relatively high doses, behaving as cachexia‐inducing factors, and that S100B and HMGB1 are massively released from tumour masses." (PMID 32159297, 2020). "Dasatinib-treated mice maintained ERα status and reduced primary tumor expression of p-Src kinase, the co-activator SRC-1, the transcription factor HOXC11, and their target gene S100β." (PMID 28399921, 2017). "Meghnani and colleagues also reported an up‐regulation of the RAGE ligands S100B, S100A2, S100A4, S100A6 and S100A10 in RAGE overexpressing tumours." (PMID 26928771, 2016). "On the other hand we found that in patients with truly positive tumor markers the median survival is shorter compared to patients positive for recurrence only in PET/CT, indicating that S100B and MIA detect subgroups of metastasis with poor prognosis." (PMID 21935432, 2011). "Finally, the markers involved in the epithelial-mesenchymal transition, including S100B, SMA, and p-S6, were decreased in tumor epithelial samples compared to matching benign epithelium from the same sections." (PMID 40729351, 2025).